AKT3 (AKT serine/threonine kinase 3)
Diseases named in the same sentence as AKT3 in open-access papers (continued):
Sharing a sentence is not in itself a finding about the gene and the disease.
schizophrenia (continued). "Ablation of AKT2 in mice was linked to anxiety and depression-like behaviors, while ablation of AKT3 resulted in small brains and schizophrenia-like symptomatology." (PMID 35525984, 2022). "Genome-wide association studies identified a strong correlation between the AKT3 gene locus and schizophrenia, where patients’ brains had lower expression levels of AKT3 protein." (PMID 35813062, 2022). "AKT3 was upregulated by all four antipsychotics, potentially reversing the downregulation seen in post-mortem brains from people with schizophrenia." (PMID 35886854, 2022). "It has a major role in brain development and the AKT3 knock-out mice exhibited a phenotype reminiscent of psychiatric manifestations including schizophrenia." (PMID 35886854, 2022). "AKT3 is likely crucial for cognition and behavior, as GWAS studies have identified AKT3 in the manifestation of schizophrenia (Schizophrenia Working Group of the Psychiatric Genomics 2014)." (PMID 34296180, 2021). "Schizophrenia, for example, has been associated with SNPs in AKT1 and AKT3, reduced AKT1 levels in patient brains, and pathogenic AKT signaling." (PMID 33325370, 2020). "In consistent with this, AKT3 KO mice have demonstrated a phenotype reminiscent of depression and schizophrenia." (PMID 30781836, 2019). "Contemporary psychiatric genetic studies have identified polymorphic variation in the AKT3 gene, including a putative functional SNP (rs14403) in the 3 untranslated region (UTR) of transcript NM_005465, as genome-wide associated to schizophrenia." (PMID 28467426, 2017). "In fact, Akt3 deletion rather evokes changes in mouse behavior reflecting psychiatric manifestations reminiscent of schizophrenia, anxiety and depression." (PMID 28442992, 2017). "However, our findings seem to conflict, as AKT3 expression is increased in postmortem prefrontal cortices in individuals diagnosed with schizophrenia." (PMID 36386965, 2022). "To complement the robustness of finding therapeutic relevant gene targets, we compared with evidence from GWAS and found three schizophrenia-associated eQTL genes in the two main clusters of the PPI networks (i.e., PDCD10 and AKT3 in cluster 1, ANK2 in cluster 2)." (PMID 35886854, 2022). "While the loss-of-function variants of AKT3 did not confer risk for schizophrenia, we characterized AKT3-Q60H because of its location in the PH domain and potential functional consequences." (PMID 35525984, 2022). "Although the AKT3/1q44 locus has been associated with schizophrenia risk, the mechanisms are not yet known given that AKT3 is involved in many biological functions." (PMID 31554518, 2019). "It is remarkable that studies have identified AKT3 as a potential contributor to schizophrenia." (PMID 30781836, 2019). "It is noteworthy that a multi-stage schizophrenia genome-wide association study has identified Akt3 as a potential contributor to schizophrenia, which underscore the importance of investigating the role of Akt3 in the brain (Schizophrenia Working Group of the Psychiatric Genomics Consortium, 2014)." (PMID 28442992, 2017). "Altogether, our data paired with these recent evidences raise the interesting possibility that Akt3 might play a pivotal role in human brain pathologies such as schizophrenia, depression and anxiety." (PMID 28442992, 2017). "Altogether, these results suggest that while Akt3 deletion is associated with an endophenotype reminiscent of schizophrenia, anxiety and depression, the Akt3/GSK3 signaling has no influence in hippocampal area CA1 functions." (PMID 28442992, 2017). "Therefore, the involvement of the Akt3 isoform in mice behaviors related to schizophrenia and mood disorders is novel and highly relevant." (PMID 28442992, 2017). "Our data in Akt3 KO mice, showing preserved normal glucose homeostasis and body weights, demonstrate an endophenotype reminiscent of schizophrenia, depression and anxiety." (PMID 28442992, 2017).
schizophrenia (continued). "There was decreased PI3K expression in the animal and cell models of schizophrenia, down-regulated PI3K mRNA expression and increased AKT mRNA expression in the peripheral blood of schizophrenic patients, and increased susceptibility of schizophrenic symptoms in AKT3-deficient mice." (PMID 37013544, 2023). "No enrichment of coding AKT3 variants in schizophrenia patients was identified." (PMID 35525984, 2022). "Thus, a dysregulation of Akt3 expression is observed, knowing that the invalidation of this gene in mice revealed an endophenotype reminiscent of psychiatric manifestations such as schizophrenia, anxiety, and depression." (PMID 36362329, 2022). "We illustrate multiple isoTWAS associations undetectable at the gene-level, prioritizing isoforms of AKT3, CUL3 and HSPD1 in schizophrenia and PCLO with multiple disorders." (PMID 38036788, 2023). "The protein-protein interaction (PPI) networks found two main clusters having schizophrenia expression quantitative trait loci (eQTL) genes such as PDCD10, ANK2, and AKT3, suggesting further investigation on these genes as potential novel treatment targets." (PMID 35886854, 2022). "In addition, AKT3 might also play a pivotal role in human brain pathologies such as schizophrenia." (PMID 30781836, 2019). "Since cognitive deficits remain a significant therapeutic problem in schizophrenia, these findings highlight the AKT signaling pathway and Akt3 specifically, as a biologically relevant therapeutic target." (PMID 28467426, 2017). "Of these, 7 have never been tested in clinical trials for schizophrenia or other psychiatric disorders (e.g., AKT3)." (PMID 41639063, 2026). "For instance, Akt3 KO mice exhibited reduced prepulse inhibition and social novelty, two phenotypes often seen in animal models of schizophrenia." (PMID 28442992, 2017). "Our data in mouse provide support for this hypothesis and demonstrate that reductions in Akt3 can result in attenuated brain AKT activity and phenotypic outcomes similar to observations in schizophrenia." (PMID 28467426, 2017). "Together, these data implicate an indispensable and non-redundant role for Akt3 in brain development and cognitive function and identify neurobiological mechanisms of relevance to schizophrenia." (PMID 28467426, 2017). "It is important to note that it is currently unknown whether the decrease in AKT Ser473 phosphorylation observed in patients with schizophrenia is accounted for by alterations in the activity of AKT1, AKT2 or AKT3." (PMID 28467426, 2017). "Furthermore, evidence from postmortem brain and peripheral cells of patients with schizophrenia has identified reduced AKT activity, either through reduced expression of AKT1, AKT3 or phosphorylated AKT Ser473." (PMID 28467426, 2017). "This study found that prenatal Poly I:C challenge led to an increased mRNA expression of AKT1, AKT3, and GSK3β in the DRN; therefore, our findings provided the first evidence in the DRN to support the proposition that alterations in AKT‐GSK3β signaling contribute to schizophrenia pathogenesis." (PMID 40562368, 2025). "Some schizophrenia eQTL genes such as PDCD10, ANK2 and AKT3 with highly connected functions to these pathways should be further investigated to find out how they and their related pathways are involved with the disease, which might potentially enable the finding of novel treatment targets." (PMID 35886854, 2022).
hepatocellular carcinoma (21 papers, 2008 to 2024). A malignant tumor that arises from hepatocytes. "Other studies have revealed that miR-122 is a tumor suppressor through modulating oncogenes including CDK4, cyclin G1, and AKT3 in hepatocellular carcinoma (HCC)." (PMID 35651814, 2022). "It should also be noted that LINC00680 can also sponge miR-568 to upregulate the expression of AKT3 in hepatocellular carcinoma to enhance carcinogenetic stemness behavior and chemoresistance." (PMID 35255921, 2022). "It was found that human miR-568 targets AKT3/mTORC to regulate hepatocellular carcinoma stemness and response to chemotherapy." (PMID 36092152, 2022). "Akt3 is capable of inhibiting the proliferation and migration of hepatocellular carcinoma, and its mRNA is a known target of miR-582-5p and miR-424." (PMID 32849388, 2020). "Activation of the C19MC miR-519d was shown to target CDKN1A/p21, PTEN, AKT3 and TIMP2, and is closely associated with the pathogenesis of hepatocellular carcinoma by promoting cell proliferation and invasion, and in inhibiting apoptosis." (PMID 28270145, 2017). "Our previous study identified AKT1, AKT2 and AKT3 as unfavorable prognostic factors for patients with hepatocellular carcinoma (HCC)." (PMID 25424347, 2014). "In primary hepatocellular carcinoma, AKT3 was up-regulated as a result of a gained 1q44 region." (PMID 19759907, 2009). "A previous study showed that miR-122 acts as a tumour suppressor by regulating oncogenes such as cyclin G1, AKT3, and CDK4 in hepatocellular carcinoma." (PMID 38820252, 2024). "In hepatocellular carcinoma, miR-582-5p exerts growth-suppressive effects through negative regulation of CDK1 and AKT3." (PMID 34978519, 2021). "The miRNA miR-582-5p is known to suppress the proliferation of a variety of tumors, including hepatocellular carcinoma, colon cancer, and bladder cancer, and this suppression is thought to be related to the target genes CDK1, AKT3, Rab27a, and FOXC1." (PMID 31146370, 2019). "Previous studies have shown that miRNA-424-5p suppresses the expression of SOCS6 in pancreatic cancer and inhibits the Akt3/E2F3 axis and tumour growth in hepatocellular carcinoma." (PMID 29716627, 2018).
triple-negative breast carcinoma (20 papers, 2013 to 2024). An invasive breast carcinoma which is negative for expression of estrogen receptor (ER), progesterone receptor (PR), and human epidermal growth factor receptor 2 (HER2). "Depletion of Akt3 in triple-negative breast cancer (TNBC) cells increased cell migration and metastases formation in mice by upregulation of S100A4." (PMID 38291468, 2024). "In triple-negative breast cancer, knockdown of AKT3 inhibits tumor spheroid growth in three-dimensional (3D) and in xenografts via significant elevation of cell-cycle inhibitor p27." (PMID 35499128, 2022). "Increasing attentions have been paid to the role of circRNAs in the etiology of triple-negative breast cancer (TNBC), and we strived to figure out the association of circRNA AKT3/miRNA axis with TNBC chemo-resistance." (PMID 33495420, 2021). "This points to an important role of AKT3 in bone-metastasizing triple negative breast cancer cells that, to our knowledge, is reported here for the first time." (PMID 33670586, 2021). "Because reduced AKT3 expression levels in triple-negative breast cancers are reported to increase sensitivity to GSK690693, FPKM values of AKT1/2/3 were checked in GUMC220/221." (PMID 29419396, 2018). "We demonstrated that knockdown of AKT3 can increase the metastatic potential of triple negative breast cancer cells." (PMID 26741489, 2016). "In addition, other authors identified AKT3 as a key factor inducing tumor growth and invasiveness in ovarian and other neoplasms, including triple-negative breast cancer, which highly resembles the features of HGSOC." (PMID 35053468, 2022). "In triple negative breast cancers, increased AKT3 expression is prevalent and may be driven by gene amplification." (PMID 28082369, 2017). "Furthermore, AKT3 depletion sensitizes triple negative breast cancer cells to the pan-AKT inhibitor GSK690693." (PMID 28082369, 2017). "Targeting AKT3 may be an effective approach to inhibit the growth of triple-negative breast cancer." (PMID 27903978, 2017). "MAPKAPK3, AKT3, CDK5, IGF1R, and MAPK11 are potential prognostic markers and therapeutic targets of curcumin in patients with triple-negative breast cancer." (PMID 37569854, 2023). "Recently, AKT3 was shown to be frequently overexpressed in triple negative breast cancer (TNBC), suggesting that AKT3 might drive the progression of triple-negative breast cancer." (PMID 26741489, 2016).
microcephaly (19 papers, 2011 to 2025). "That WDR62 mutations are associated with microencephaly is an interesting tie in with mutations in Akt3 in MPPH syndrome." (PMID 40048438, 2025). "Human mutations that cause constitutive activation of Akt3 result in macrencephaly, while in both humans and mice, null mutations cause microencephaly." (PMID 40048438, 2025). "In this study, the findings in patients 1, 2, and 3 would support the conclusion that haploinsufficiency of AKT3 gene is indeed associated with microcephaly." (PMID 30853971, 2019). "Mutations that result in enhanced AKT3 activity lead to increased brain growth, while deletion of AKT3 is involved in microcephaly." (PMID 29173281, 2017). "Several clinical studies demonstrate that haploinsufficiency of AKT3 in this region causes microcephaly and ACC." (PMID 28025777, 2017). "Previous genotype-phenotype correlation studies suggested that microcephaly is mainly associated with AKT3 haploinsufficiency." (PMID 28283832, 2017). "They concluded that AKT3 haplo-insufficiency causes both postnatal microcephaly and agenesis of the corpus callosum." (PMID 21936942, 2011). "Interestingly, microcephaly has been reported in nearly the half of 1q43q44 deletion patients and suggesting that AKT3 haploinsufficiency is the main cause of microcephaly in this syndrome." (PMID 36192753, 2022). "In addition, characters of animals with the AKT3 deletion have shown microcephaly, whereas high-AKT3 activities are associated with macrencephaly." (PMID 30781836, 2019). "Akt3 is the predominant Akt isotype in the adult brain, transcription is enriched in human fetal neocortex and haploinsuffiency in humans is linked to cortical malformations, including microcephaly and cognitive dysfunction." (PMID 28467426, 2017). "Of thesegenes, AKT3 gene haploinsufficiency has been linkedwith microcephaly in previously reported cases with1q43q44 deletion syndrome." (PMID 31210441, 2019). "A SOX2-bound neural enhancer within the Akt3 gene is connected to the Zbtb18 (ZFP238 in man) TF gene, whose mutation causes microcephaly in man and mouse; in man, deletions including AKT3, or translocations separating AKT3 from ZFP238 also cause microcephaly." (PMID 30849367, 2019). "AKT3 was included in 24/26 deletions identified in individuals with microcephaly, whereas only 2/23 patients with microdeletions sparing AKT3 had microcephaly (p = 1.46E−9)." (PMID 28283832, 2017). "The minimal critical region for microcephaly (g.243,778,438–g.244,125,269) mapped to a region encompassing the 5′ upstream region and the five first exons of AKT3." (PMID 28283832, 2017). "Our study demonstrates that AKT3 haploinsufficiency is the main driver for microcephaly, whereas HNRNPU alteration mostly drives epilepsy and determines the degree of intellectual disability." (PMID 28283832, 2017). "Our data confirm that AKT3 is the main gene driving microcephaly, ZBTB18 defect is responsible for AnCC and HNRNPU is the main gene accounting for epilepsy." (PMID 28283832, 2017). "The occurrence of microcephaly in patients with microdeletions restricted to AKT3 narrows the minimal critical region to this single gene." (PMID 28283832, 2017). "Fetoscopy showed evidence of microcephaly which is in agreement with the implication of AKT3 in MIC as has already been proposed by others." (PMID 25722899, 2015). "The first encompassing ZNF238 was associated with corpus callosum anomalies (CCA) and the second includes AKT3 with microcephaly (MIC), while the third contains the two coding genes FAM36A, HNRNPU and the noncoding gene NCRNA00201 with seizures." (PMID 25722899, 2015). "Recently, 1q43 has been proposed as a candidate region for microcephaly, in particular AKT3 has been considered as a candidate gene for this feature in patients with a microdeletion of 1q43-q44." (PMID 25223409, 2014). "This emphasizes the association AKT3 -microcephaly in the 1q44microdeletional syndrome rather than its links with CCA." (PMID 36192753, 2022).
microcephaly (continued). "Four of the six deletions including coding sequences of AKT3 only and one of the two deletions encompassing ZBTB18 but not AKT3 were associated with microcephaly." (PMID 28283832, 2017). "AKT3 may be the primary target for mTORC2 activity, as ablation of the mTOR2 complex proteins Rictor and Sin1 was shown in mice to decrease AKT Ser473 activation, causing microcephaly and alterations in neuronal morphology and function." (PMID 35525984, 2022). "The “bait” network contained genes such as AKT3, considered the underlying cause for the microcephaly in patients with the 1q44 microdeletion syndrome, and MAPK1, involved in neurogenesis and located within the distal 22q11 deletion frequently associated with microcephaly." (PMID 25781962, 2015). "AKT3 (1q43-q44; MIM 611223) deletions lead to partially penetrant microcephaly although the contribution of ZBTB18 (1q44; MIM 608433) and HNRNPU (1q44; MIM 602869) mutation is possible." (PMID 32916978, 2020). "Deletions of chromosome 1q42-q44 (encompassing the AKT3 gene) in human genome have been reported in a variety of developmental aberrations of the brain, including agenesis of the corpus callosum (ACC) and microcephaly." (PMID 28025777, 2017). "The observation of two patients and a healthy father with microdeletions limited to AKT3 and normal brain size suggests that AKT3-related microcephaly is not fully penetrant." (PMID 28283832, 2017). "The preponderant role of AKT3 in microcephaly does not exclude minor involvement of other genetic determinants." (PMID 28283832, 2017). "The alignments of microdeletions found in patients with a known OFC and comparison of their gene content showed that microcephaly was present in all 20 patients with deletions encompassing both AKT3 and ZBTB18, regardless of the presence of HNRNPU in the deletions." (PMID 28283832, 2017). "Alternatively, the fact that AKT3 deletions in patients with normal OFC alter the 3′ end of the gene could suggest that the region of AKT3 critical for microcephaly encompasses at least the first 5 exons but not the 3′ coding part of the gene." (PMID 28283832, 2017).